IL6 (interleukin 6)
Diseases named in the same sentence as IL6 in open-access papers (continued):
Sharing a sentence is not in itself a finding about the gene and the disease.
infection (continued). "Serum PCT, IL-6, and CRP were valuable in early infection prediction post-CAR-T therapy, particularly PCT with the highest area under the ROC curve (AUC) of 0.897." (PMID 38956649, 2024). "Taken together, our results highlight the distinctive and dynamic patterns of IFN-α, IFN-β, IL1-β, IL-6, and iNOS mRNA expressions in response to IBV DMV/1639 infection, underscoring the intricate interplay between the virus and the host TOCs." (PMID 39472003, 2024). "The levels of IL-1β, IL-6, IFN-γ and TNF-α in the PCV4-inoculated group remained elevated throughout the infection period." (PMID 39135875, 2024). "The prepared ODHP-NS-HG reverted the inflammatory effect and suppressed the infection by compromising the levels of COX-2, TNF-α, NF-κB-p105, IL-6, and IL-1β in treated group E comparing to untreated groups." (PMID 38217256, 2024). "In the present study, haemonchosis elevated IL-3, IL-6, IL-10, and TNF-α gene expressions in abomasum tissue mRNA, which was attributed to the activation of the inflammatory cascade triggered by infection." (PMID 38963478, 2024). "We observed significant increases in proinflammatory cytokines IL-6 and IL-1β in the lungs of 5-LO−/− mice, compared to levels in C57BL/6 mice, at day 7 post-infection." (PMID 39082787, 2024). "Representative pro-inflammatory cytokines, including IL-1β, IL-6, and TNF-α, are secreted upon infection and tissue damage, promoting the migration of immune cells to the inflammatory site and amplifying the inflammatory response." (PMID 39727927, 2024). "On the fifth day after infection, a high dose of GUANKE reduced the induction of TNF-α, IL-1β, IL-6, and IL-17." (PMID 39431894, 2024). "When recognized by epithelial cells, endothelial, and alveolar macrophages, proteins such as IL-6, IP-10, and MCPI, are released which attract T cells, macrophages, and monocytes to the site of infection, promoting inflammation." (PMID 38236918, 2024). "Exposure to PM10 followed by infection significantly elevated relative mRNA levels for TNF-α, IL-1β, CXCL2, TLR4, IL-6, COX2, and iNOS when compared to control air (p < 0.001 for all)." (PMID 38928968, 2024). "In particular, the prognostic role of GDF-15 was more reliable in the early phase of the infection, when compared with other inflammatory biomarkers, including CRP, ferritin, D-dimer, and IL-6." (PMID 38700782, 2024). "Infection-related biomarkers such as hs-CRP, PCT and IL-6 levels are commonly utilized laboratory indicators in diagnosing and treating infectious lung diseases." (PMID 38576608, 2024). "IL-6 and TNF-α are cytokines that are promptly and transiently produced in response to infections and tissue injuries." (PMID 38611807, 2024). "These factors encompassed complications; locations of infection; the history of amputation; vascular CTA; levels of albumin, creatinine, and cholesterol; counts of white blood cells; hemoglobin levels; and interleukin-6 levels." (PMID 39735416, 2024). "In order to investigate the role of JTY_0672 in the inflammatory response, we considered the colonization data from organs, and measured the levels of IL-1β, IL-6, TNF-α, and INF-γ in the sera of mice on day 7 after infection." (PMID 39845031, 2024). "From day 5 to 21, this patient suffered anti-infection treatment using meropenem, and the infection indicators (CRP, WBC, NEU, IL-6, and PCT) were measured." (PMID 39203510, 2024). "E. tenella infection lead to upregulation of pro-inflammatory cytokines as IFN-γ, IL-1β, IL-6 and anti-inflammatory cytokines as TGF-β4 following primary infection, while their expression was downregulated following secondary infection." (PMID 38492183, 2024). "The infection model in goats was established and validated by the fecal egg count (FEC) test and qPCR analysis of the gene expression of IL-5 and IL-6." (PMID 38786064, 2024).
infection (continued). "Collectively, these findings indicate that EIIB in L. monocytogenes LIPI-4 stimulates the release of inflammatory factors IL-1β, IL-6, IL-10, and TNF-α to combat infection." (PMID 39057985, 2024). "Inflammatory cytokine assays demonstrate that compared to the mock group, IL-1β, IL-6, IL-8, and TNF-α were significantly upregulated in the lungs, spleen, intestines, and brain post-infection." (PMID 39170631, 2024). "First, we determined the quantity of production for IL-1β, IL-6, and TNF-α in the lung as the primary site of infection." (PMID 38646937, 2024). "Infection of BRB with ZIKV leads to the generation of IL-1β, IL-6, IFN-α, IFN-β, TNF-α, CCL5 and CXCL-10." (PMID 39795906, 2024). "To determine if CETP inhibition regulates proinflammatory cytokine production at the transcriptional level, we examined the mRNA levels of IL-6, IL-1β, and TNF-α using quantitative PCR (qPCR) at 72 hours after infection." (PMID 38646937, 2024). "At 48 h of infection, the gene expression of CXCL10, TNF-α, IL-8, and IL-6 was increased up to 47.14-fold, 26.43-fold, 10.87-fold, and 3.45-fold, respectively, while the COX-2 gene was expressed 70.70-fold after 72 h of dengue viral infection." (PMID 39200005, 2024). "Based on the results, the mRNA levels as well as IL-1β, IL-6, IL-8, IL-10, IL-18, TNF-α and IFN-γ were significantly upregulated, and the IL-2 level was decreased in the infection group compared to the control group (p < 0.05)." (PMID 38582846, 2024). "Monocytes travel throughout the bloodstream, detecting and responding to infections or other stimuli by producing inflammatory cytokines such as TNF-α, IL-1β, IL-6, IL-8, IL-10, and IL-12." (PMID 39042701, 2024). "IL-6 and TNF-α are typical cytokines secreted by M1 macrophages; in the early stage of infection and tissue injury, IL-6 and TNF-α were rapidly produced to stimulate the immune response." (PMID 38731567, 2024). "Further longitudinal studies are needed to understand the dynamic changes in arachidonic acid, IL-6, and CRP levels during infection and recovery." (PMID 39066228, 2024). "On the other hand, the increased levels of C3, IL-6, IL-12, TNFα and CXCL1 as a means of activation of innate-mediated response in early infection phases have been found in SARS-CoV-2-infected Caco-2 cells." (PMID 38886736, 2024). "In this multicentre retrospective study, we developed and validated a new predictive score based on five variables (age and IL-6, BUN, D-dimer, and LDH levels) to predict outcomes in patients with SARS-CoV-2 Omicron infection." (PMID 38961438, 2024). "TNF-α, IFN-γ, IL-1β, IL-6, and MIF are pro-inflammatory molecules that activate immune cells and defend against infection." (PMID 38572322, 2024). "E2 treatment post-infection significantly decreased the mRNA expression of inflammatory genes IL-1β, IL8, IL6 and TNF-α compared to the E. coli infected group (P < 0.05)." (PMID 39600797, 2024). "The biomarkers, including PCT, IL-6, CRP, and their combination, can help confirm a diagnosis of infection." (PMID 38956649, 2024). "The iNOS is one of nitric oxide synthesis (NOS) enzymes that catalyzes NO production, and COX-2 regulates the production of NO and pro-inflammatory cytokines such as IL-6, IL-1β, and TNF-α to facilitate pathogen clearance during infection." (PMID 38213288, 2024). "To test this, we employed HH inhibitor GANT61, and the reagent blocked the rTGFβ1 effects on hBMECs, and rTGFβ1 treatment was incapable of reducing the upregulation of IL-6, MIP-2, and E-selectin upon RS218 infection." (PMID 38360663, 2024). "S. aureus exposure did not increase the capacity of macrophages to directly kill intracellular E. coli but instead promoted IL-6, TNF, and IL-1β production by these cells, leading to enhanced recruitment of neutrophils to clear the infection." (PMID 39618498, 2024).
infection (continued). "We observed significantly higher levels of IL-6 and TNF-α in both serum and lungs of DDX5+/- mice than that in DDX5+/+ mice following infection with P. multocida and S. aureus for 0–12 h, and M. pneumoniae for 0–24 h." (PMID 38182816, 2024). "Infection of THP-1 cells with A.baumannii significantly induced cellular production of TNF-α and IL-6, and the positive control PMB significantly inhibited the production of inflammatory factors." (PMID 38956179, 2024). "Group I showed greater numbers of all CCR6+ B-cell subsets and CXCR3+ naive B cells and plasma cells than did Group C. Infection of the nurslings promoted increased CCL20, CXCL10, IL-6, IL-8, total IgA, and IgG levels in the milk." (PMID 39867906, 2024). "An increase in pro-inflammatory cytokine production was detected in homogenized lung supernatants including IFN-γ, IL-1β, IL-6, IL12-p40 and IL-17 at three- and four-weeks post-infection." (PMID 38198478, 2024). "Our data revealed that IL-6 was the first to be released in CV-A10-infected HMC3 cells at 6 h after infection, then IL-8 was also found to begin to be released at 12 h after infection." (PMID 38641810, 2024). "All groups of immunized mice had decreased levels of IL-6, IFN-γ, and IL-17 in the lung cells after infection." (PMID 38400107, 2024). "We used Ms-pVV2 and Ms-PE_PGRS38 for infection of RAW264.7 macrophages to study their effects on TNF-α, IL-1β, IL-6, and IL-10 mRNA expression." (PMID 38785795, 2024). "We also tested IL-6 expression in lungs derived from SARS-CoV-2-infected hamsters and SARS-CoV-2-infected hamsters treated with SNAT, 3 days post-infection." (PMID 39058147, 2024). "In parallel, infection of TOCs with IBV DMV/1639 resulted in a marked increase in IL1-β mRNA expression at 3, 6, and 12 hpi (P < 0.05) and IL-6 mRNA expression at 3 and 6 hpi (P < 0.05) compared with both IBV Conn A5968-infected TOCs and non-infected controls." (PMID 39472003, 2024). "The efficacy of IL-6 detection for the early diagnosis of wound infection was proposed, considering the ability of IL-6 to activate C-reactive protein (CRP), a well-known biomarker for evaluating infection status." (PMID 39064129, 2024). "We found Trim26–/–mice had higher levels of proinflammatory cytokine expression than Trim26+/+ mice, including IL-6, IL-1β, and TNF-α at day 5 post-infection." (PMID 38166150, 2024). "There is an increased recruitment of MHCII-Ly6C+ monocytes to the infection site and an increase in inflammatory mediators such as TNF-α, IL-12, IL-23, IL-1b and IL-6, as well as activation of other inflammatory cells, including Th1 or Th17 cells." (PMID 39081865, 2024). "There was a significant increase in in the secretion of cytokines IL-2, IL-6, IL-10, TNF-α, and IFN-γ in the H3N2 virus-infected group 24 hours after infection." (PMID 37900310, 2023). "In the presence of infection, untreated HTR8/SVneo cells, as well as cells treated with the hydroalcoholic extract or oleoresin, increased the levels of IL-6 in relation to the medium or SDZ + PYR-treated cells, respectively (#P < 0.05, &P < 0.05)." (PMID 36860986, 2023). "Infection by Alpha resulted in significant increase of several inflammatory cytokines such as CCL2, CXCL10 and IL-6 over a longer period of time compared to Ancestral strain." (PMID 37507719, 2023). "Our findings revealed that inflammatory cytokines, including TNF-α and IL-6, Th1-related cytokine IFN-γ, and Th2-related cytokine IL-5 were significantly elevated in HD patients after breakthrough infection compared to after booster immunization." (PMID 37515030, 2023). "In this study, we detected the increased presence of serum cytokines IL-6, TNF-α, and IL-1β after the infection." (PMID 37256132, 2023). "Prior to infection, the disease protective latent condition presented the cytokine panel with mild or moderate levels of TNF-α, IFN-γ, IL-2, IL-17, and IL-6." (PMID 36646786, 2023).
infection (continued). "Interleukin-1 (IL-1), Interleukin-6 (IL-6), Tumor Necrosis Factor-alpha (TNF-α), and Interferon-gamma (IFN-γ) are critical to cytokine storm/CRS resulting from infection/immunotherapy respectively." (PMID 37304291, 2023). "IL-6, neutrophil count, % neutrophils, NLR, PLR, CRP, AST, and urea increased with the severity of the infection." (PMID 36838284, 2023). "We analyzed the effect of PACAP pre-treatment on pro-inflammatory cytokines IL-1β, IL-6, TNF-α, and IFN-γ in RTS11 cells after challenge with Y. ruckeri at day 3 post-infection (day 4 after PACAP exposure)." (PMID 37887185, 2023). "In the present study, the two S. parasuis strains sequentially induced the upregulation of IL-6, TNF-α, and MCP-1 gene transcription in the brains of mice with neurological symptoms from 24 h post-infection." (PMID 37111486, 2023). "The mRNA expression levels of IL-6, IL-18, IFN-α, IFN-β, and ISG-15 were up-regulated during EV-G/YN23/2022 infection, while IL-1β, TNF-α, IFN-λ3, and IRF-7 maintained in relatively constant levels, and no cytokines were significantly reduced." (PMID 37632087, 2023). "Specifically, 2 weeks after infection, we observed higher levels of some cytokines involved in Th1 (TNF-α) and Th17 (IL-6 and IL-17) in the lungs of anti-Gr1-treated mice compared with those in the IgG2b-treated control group." (PMID 36776848, 2023). "Upon infection, macrophages are activated to induce the expression of type I IFN and proinflammatory cytokines such as IL-6 and TNF-α." (PMID 38005948, 2023). "Immunohistochemistry demonstrated a strong IL-6 expression in neurons, which are also a major target of TMEV infection." (PMID 36872323, 2023). "We thus compared the expression levels of proinflammatory cytokines Tnf, Il6, Il1b, and the anti-inflammatory cytokine Il10, in the lung tissues between the DMI-treated and vehicle-treated control mice during infection." (PMID 36882813, 2023). "CRP has served as a useful marker of infection and tissue inflammation for several decades, and has been shown to be regulated by the pro-inflammatory cytokines TNF-α and IL-6 in an in vitro study." (PMID 36936907, 2023). "Blood levels of inflammatory markers such as interleukin 6 (IL-6) and C-reactive protein (CRP), as well as white blood cell (WBC) count, rose during the infection's acute period (D1 and D3)." (PMID 37932342, 2023). "IL-6 and CRP were both increased in infants diagnosed with postnatal infection, with peak levels observed on days 2 and 3, respectively." (PMID 37606448, 2023). "The levels of interleukin (IL)-6, IL-1β, and tumor necrosis factor α (TNF-α) after infection with ΔadcAΔlmb at 9 and 12 h were significantly lower than those after WT infection." (PMID 37212676, 2023). "M1 macrophages produce pro-inflammatory cytokines, such as IL-1β, IL-6, IL-12, and TNF-α, which help to activate and recruit other immune cells to the site of infection or tissue injury." (PMID 37507898, 2023). "In this regard, the levels of circulating pro-inflammatory mediators such as IL-1β, IL-6, TNF-α, and IFN-γ increase in both homeostatic situations and in response to infections in the elderly compared with adults." (PMID 37654571, 2023). "Bacterial colonization and infection elicit an inflammatory reaction such as HCA, and increased levels of neutrophil infiltration, IL-6 and TNF-α, which are some of the classic signs of amniotic infection and inflammation." (PMID 37600782, 2023). "In the present study, following infection with Salmonella Enteritidis, the levels of IL-1β, IFN-γ, TNF-α, and IL-6 rose dramatically, which is consistent with the findings of earlier research." (PMID 37990191, 2023). "CRP is a plasma protein that is synthesized in the liver, induced by IL‐1, IL‐6, and TNF‐α, and considered a marker for inflammation, infection, and tissue injury." (PMID 36314077, 2023).
infection (continued). "The author proposed that the phenomenon was probably due to 1) a downregulation of CYP enzyme activities which primarily seems to be mediated by IL-6, during infection and inflammation and/or 2) an increase in AAG during infection and inflammation." (PMID 36942294, 2023). "The colonic cytokine contents were analyzed, and it was detected that CR infection promoted the pro-inflammatory factors IL-1β, TNF-α, IL-6, and IL-17A (p < 0.01), as well as the anti-inflammatory factors IL-4 (p > 0.05) and IL-10 (p < 0.01)." (PMID 37111225, 2023). "It was reported that EC infection in broiler chickens increased the expression of some proinflammatory cytokines including interleukins (ILs), such as IL-1, IL-6, and IL8, to alert the immune system against the source of inflammation or infection." (PMID 36766252, 2023). "The levels of IL-6 in both primary astrocytes and BV2 cells infected with the two S. parasuis strains peaked at 18 h post-infection and then gradually decreased at 24 h post-infection." (PMID 37111486, 2023). "As a result, the secretion of anti-infection cytokines including IFN-γ and IL-6 was significantly inhibited; T. gondii, therefore, can survive and multiply successfully in the host cells." (PMID 37909781, 2023). "Both IL-6, a pro-inflammatory and anti-inflammatory cytokine, and PCT, a calcitonin precursor, function as markers of inflammation and infection." (PMID 37176751, 2023). "Multiple biomarkers, including IP-10, IL-6, sCD163, leptin, IL-8, and LBP were variable either within each participant’s two pre-infection or two post-ART-suppression specimens." (PMID 37461626, 2023). "Infection of WT and TRPV1-/- mice significantly increased colonic Il6 and Tnfα expression compared to uninfected controls." (PMID 38109366, 2023). "This underscores IL-6’s potential as a valuable tool to ascertain the likelihood of CRP elevation and therefore the probability of infection, particularly in patients undergoing regular blood tests." (PMID 38255366, 2023). "RT-PCR data showed that the titers of all three inflammation-related genes (IL-6, IL-1β, and TNFα) were upregulated upon SARS-CoV-2 Delta-spike PV infection and decreased upon treatment with compounds K-4 and M-4." (PMID 36855173, 2023). "During the early phase of UPEC infection, the host cells release different factors, such as cytokines and chemokines (IL-1β, IL-6, IL-8 and TNF-α) and hormones (norepinephrine, estradiol), to fight off the infection." (PMID 37759520, 2023). "BCG infection significantly stimulated both splenic cDC and pDC to produce IL-6, IL-10, IL-12p70, MCP-1, and TNF-α, especially at 4 h and 12 h post-infection, whereas naive DCs secreted negligible amounts of these cytokines." (PMID 36977141, 2023). "We found that TMAO aggravated the release of several key cytokines (IL-1β and IL-6) and chemokines (IL-8, CXCL1 and CXCL6) from bladder epithelial cells during a CFT073 infection." (PMID 37111409, 2023). "The higher levels of neutrophils, NO, IL-6, and TNF-α in lesions contaminated by S. aureus demonstrate this deleterious role of infection during the inflammatory phase." (PMID 36770872, 2023). "Following secretion of chemokines and cytokines such as IL-1β, IL-6, TNF-α, IL-21, and IL-8, the SARS-CoV-2-induced cytokine storm and hyperinflammatory response have pivotal roles in infection severity, AKI development, and death." (PMID 37026010, 2023). "For example, NLRX1 negatively regulates infection-induced IFN-I signaling and IL-6 production in primary MEFs by inhibiting the interaction between MAVS and RIG-I." (PMID 37528226, 2023). "As depicted in, TNF-α, IL-6, IL-8, IL-10, IL-13, and IL-33 in children with HRSV were significantly increased in severe infection compared to mild infection (p < 0.05)." (PMID 37239461, 2023).